TWIST1 (twist family bHLH transcription factor 1)
Diseases named in the same sentence as TWIST1 in open-access papers (continued):
Sharing a sentence is not in itself a finding about the gene and the disease.
hypopharyngeal carcinoma (3 papers, 2014 to 2025). Carcinoma, predominantly squamous cell, arising from the epithelial cells of the hypopharynx. "In head‐and‐neck cell lines, TWIST1 was found to be an essential downstream target of HIF‐1α and that knockdown of TWIST1 led to a decreased number of metastatic nodules after either tail vein injection or orthotopic transplantation of hypopharyngeal cancer cell line with overexpression of HIF‐1α." (PMID 28085222, 2017). "Therefore, Twist1 knockdown may be a promising treatment regimen for advanced hypopharyngeal carcinoma patients with MDR." (PMID 24805866, 2014). "In the present study, the upregulation of MDR1/P-gp and Twist1 in MDR FaDu/T cells was detected, which suggest the expression levels of MDR1/P-gp and Twist1 were positively correlated with MDR progression in hypopharyngeal carcinomas." (PMID 24805866, 2014). "However, studies identifying the function of Twist1 in the chemosensitivity of hypopharyngeal carcinomas are lacking." (PMID 24805866, 2014).
invasive carcinoma (3 papers, 2011 to 2026). A carcinoma that is not confined to the epithelium, and has spread to the surrounding stroma. "Additionally, there was a positive correlation between TBX3 and SLUG, and TBX3 and TWIST1 in the invasive carcinoma." (PMID 30697731, 2019). "TWIST1 can be regulated by multiple extracellular factors through PI3K/AKT, Wnt1 and NF-κB pathways in invasive carcinoma concordant with our observations that activation of AKT by ARTN leads to increased expression of TWIST1 in ER-MC cells." (PMID 22060274, 2011).
keloid (3 papers, 2017 to 2021). An irregularly shaped, elevated mark on the skin caused by deposits of excessive amounts of collagen during wound healing. "As TWIST1 is established to be implicated in the process of epithelial mesenchymal transition and promotion of mitochondrial dysfunction and hypoxial damage, the IPA and KEGG analysis results using bulk RNA-seq data to compare keloids and controls correspond with those of the previous studies." (PMID 34639105, 2021). "Moreover, TWIST1, an important paralog of TWIST2, was involved in the fibrogenesis of keloid fibroblasts, and might serve as a therapeutic target of keloid, suggesting that TWIST2 might also be considered as a promising therapeutic target in HS." (PMID 35047019, 2021).
lung diseases (3 papers, 2019 to 2022). "Modulation of endothelial Twist1 would potentially be a new strategy for aging-associated lung diseases." (PMID 33764901, 2021). "Modulation of Twist1 expression in ECs could be one of the promising strategies for age-related lung diseases and may be able to delay the aging processes in the lungs." (PMID 33764901, 2021).
Nephropathy (3 papers, 2016 to 2021). A nonspecific term referring to disease or damage of the kidneys. "To test the role for quercetin in ameliorating tubular cell EMT in the kidneys with UUO nephropathy, we detected the mRNA expression for Twist1, Twist2, Snail1 and Snail2 in the kidneys at 2 weeks after UUO surgery." (PMID 27052477, 2016). "We then confirmed glomerular expression of Twist1 in murine NTS- and ADR-induced nephropathy, 2 widely used models of podocyte injury and proteinuria in mice." (PMID 34369383, 2021).
pancreatic adenocarcinoma (3 papers, 2019 to 2025). "The expression levels of Twist1, TGF‐β, E‐cadherin, N‐cadherin, miR‐21, snail, slug, vimentin and VISTA genes were examined in pancreatic adenocarcinoma (PAAD) and normal pancreatic tissues by using the GEPIA2 database." (PMID 40344465, 2025). "Normalized mRNA expression data from TCGA studies of breast, prostate, lung, colorectal and pancreatic adenocarcinomas was downloaded for ZEB1, ZEB2, SNAI1, SNAI2, TWIST1, FOXQ1 and FOXC218,19." (PMID 31780722, 2019). "The expression levels of CTNNB1, RELA, TWIST1, and YAP1 in pancreatic adenocarcinoma (PAAD) tissues were higher than those in corresponding normal tissues." (PMID 40124511, 2025).
Peritoneal Fibrosis (3 papers, 2013 to 2024). Disorder characterized by a wide range of structural changes in PERITONEUM, resulting from fibrogenic or inflammatory processes. "It has been already known that the proliferation of peritoneal mesothelial cells could be affected by the Y-box-binding protein 1 (YBX1) and Twist1 proteins during the development of peritoneal fibrosis caused by high glucose." (PMID 35380292, 2022).
prostate adenocarcinoma (3 papers, 2010 to 2025). "Previous studies also implicated TWIST1 in the development and progression of PCa, showing that its expression was up-regulated in prostate adenocarcinomas and correlated with Gleason grading and increased metastatic potential." (PMID 20976069, 2010). "To determine whether TMPRSS4 expression correlates with SLUG, TWIST1, and stemness-related factors expression in human cancers, we analyzed TCGA-generated prostate adenocarcinoma data (TCGA, Firehose Legacy and TCGA, Cancer Cell 2010 studies)." (PMID 34809669, 2021).
Sezary syndrome (3 papers, 2022 to 2025). Sezary syndrome (SS) is an aggressive form of cutaneous T-cell lymphoma characterized by a triad of erythroderma, lymphadenopathy and circulating atypical lymphocytes (Sezary cells). "The expression of TWIST1 increased in the Sezary syndrome stage due to either the acquired promoter hypomethylation or the chromosomal region 7p21, which stresses its part in disease development and severity." (PMID 39941895, 2025). "further determined that TWIST1 expression in CTCL increases with disease stage from the more indolent Mycosis Fungoides stage through to the advanced Sezary syndrome stage." (PMID 37600794, 2023). "Similarly to TWIST1, TWIST2 was also found to be expressed highly in a Sezary syndrome (CTCL) cell line compared to a T-ALL cell line in one study, however no further evidence to support a role for TWIST2 in this disease has been published to date." (PMID 37600794, 2023).
stomach adenocarcinoma (3 papers, 2020 to 2023). "Moreover, Twist1 was reported to facilitate invasion and EMT in gastric adenocarcinoma." (PMID 36781842, 2023).
Stroke (3 papers, 2020 to 2024). Sudden impairment of blood flow to a part of the brain due to occlusion or rupture of an artery to the brain. "Colocalization analysis also suggested TWIST1 as a causal gene in the HDAC9/TWIST1 association locus for CAD and stroke." (PMID 31917787, 2020). "Importantly, the shared stroke and CAD association signal rs2107595 near HDAC9 colocalized with TWIST1 but not HDAC9 expression in aorta." (PMID 31917787, 2020).
Ureteral obstruction (3 papers, 2022 to 2023). Obstruction of the flow of urine through the ureter. "To further explored the mechanism of Twist1 in kidney fibrosis, we made the unexpected discovery that Twist1 is also highly expressed in renal macrophages in the unilateral ureteral obstruction (UUO) mouse model." (PMID 35182235, 2022).
urothelial carcinoma (3 papers, 2020 to 2025). A malignant neoplasm derived from the transitional epithelium of the urinary tract (urinary bladder, ureter, urethra, or renal pelvis). "In order to develop the methylation assay for detecting urothelial carcinoma, we conducted a screening of 14 CpG sites in 7 genes (HIST1H4F, SOX1-OT, Vim, Onecut2, Twist1, NRN1, POU4F2) based on the literature review." (PMID 40855090, 2025). "Abern studied the role of two methylated genes, TWIST1 and NID2 based on Renard work due to their high sensitivity and specificity for urothelial carcinoma." (PMID 32664878, 2020).
urothelial carcinoma of the bladder (3 papers, 2017 to 2025). "Our study demonstrates that the sensitivity and specificity of TWIST1/Vimentin promoter methylation in urine samples for differentiating bladder urothelial carcinoma (BUC) from benign diseases and healthy controls reached 78% and 83%, respectively." (PMID 38575639, 2024). "Additionally, KLF4 has been identified as a prognostic predictor for urothelial carcinoma of the bladder, where it regulates TWIST1-mediated epithelial-mesenchymal transition." (PMID 40299916, 2025). "Our findings reveal that hypermethylation of the TWIST1/Vimentin promoter occurs in bladder urothelial carcinoma, and its high sensitivity and specificity suggest its potential as a screening and therapeutic biomarker for urothelial carcinoma of the bladder." (PMID 38575639, 2024).
acute lymphoblastic leukemia (2 papers, 2018 to 2025). Leukemia with an acute onset, characterized by the presence of lymphoblasts in the bone marrow and the peripheral blood. "In hematological malignancies, several studies have reported on the role of the EMT transcription factors TWIST1 and TWIST2 in both myeloid and lymphoblastic leukemia." (PMID 29925392, 2018). "Moreover, the expression of TWIST1 has not yet been studied in B-cell or T-cell acute lymphoblastic leukemia (B-All/T-ALL), but it is significantly expressed in ALK+ anaplastic large cell lymphoma (ALCL) and cutaneous T-cell lymphoma (CTCL)." (PMID 39941895, 2025).
acute promyelocytic leukemia (2 papers, 2023 to 2024). An aggressive form of acute myeloid leukemia (AML), characterized by arrest of leukocyte differentiation at the promyelocyte stage, due to a specific chromosomal translocation t(15;17) in myeloid cells. "Consistently, TWIST1 levels were also observed to be high in acute promyelocytic leukemia (APL) cells, a sub-population of AML, and this event was shown to be due to its interaction with tribbles pseudokinase 3 (TRIB3), protecting it from degradation processes." (PMID 38396852, 2024).
Alzheimer disease (2 papers, 2023 to 2024). A progressive, neurodegenerative disease characterized by loss of function and death of nerve cells in several areas of the brain leading to loss of cognitive function such as memory and language. "Further, craniosynostosis exacerbates amyloid pathology and plaque buildup in Twist1+/–:5xFAD transgenic Alzheimer’s disease models." (PMID 37917195, 2023).
bone cancer (2 papers, 2018 to 2020). A primary or metastatic malignant neoplasm affecting the bone or articular cartilage. "An analysis of 206 specimens of bone tumours showed that among the indicators with diagnostic utility, including SP7, IHH, RUNX2, SOX9 and TWIST1, only RUNX2, TWIST1 and SOX9 are sensitive and specific factors that differentiate between chondroblastoma and chondromyxoid fibroma." (PMID 29899399, 2018).
Cachexia (2 papers, 2020 to 2022). Severe weight loss, wasting of muscle, loss of appetite, and general debility related to a chronic disease. "Myostatin can induce the expression of MuRF1 and Atrogin1/MAFbx as well as Twist1, and genetic inactivation of myostatin has shown to protect against cancer-induced cachexia." (PMID 32655411, 2020). "In this article, we will briefly summarize how Twist1 acts as a master regulator of tumor-induced cachexia, and discuss the relevance of our findings to muscle wasting diseases in general." (PMID 32655411, 2020). "Based on the inducible Twist1 knockout mice studies, it appears that Twist1 has rather a non-essential role in adult animals, and therefore, targeting Twist1 to manipulate tumor-induced cachexia would be a suitable drug target that is likely to exert minimal advert effects in adult patients." (PMID 32655411, 2020).
cervical squamous cancer (2 papers, 2012 to 2019). "In this sense, a study that investigated the change of Twist1 expression in human cervical squamous cancer cell line (SiHa) after hypoxia treatment observed that, hypoxia treatment elevated the expression of Twist1 in SiHa cells." (PMID 30842790, 2019). "Immunohistochemical staining showed strong cytoplasmic and/or nuclear staining for Twist1, cytoplasmic and/or membrane staining for MDR1/P-gp in both cervical squamous cell carcinoma and adenocarcinoma tissues." (PMID 22245869, 2012).
chronic myeloid leukaemia (2 papers, 2015 to 2022). "The upregulation of TWIST1 levels in chronic myeloid leukaemia (CML) promotes resistance to the therapeutic drug imatinib." (PMID 35203300, 2022).
clear cell carcinoma (2 papers, 2014 to 2016). "They found that TWIST1 expression predicts poor clinical outcomes in patients with clear cell carcinoma (CCC) of the ovary, suggesting that TWIST1 may play a critical role in the progression of CCC." (PMID 25238494, 2014).
colorectal adenoma (2 papers, 2012 to 2018). An adenoma that arises from the colon or rectum. "Colorectal adenomas positive for TWIST1 mRNA also showed a lower amount of CDH1 mRNA - the correlation was not significant (p = 0.29, Mann-Whitney-U test)." (PMID 23029563, 2012). "We could detect SNAI1 mRNA expression in 32 (78%) and TWIST1 mRNA expression in 17 (42%) of 41 colorectal adenomas." (PMID 23029563, 2012). "Here we tested whether the important regulators of E-cadherin expression SNAI1 and TWIST1 are already detectable in human colorectal adenomas." (PMID 23029563, 2012). "Therefore, further investigation might be beneficial to check the use of TWIST1 and SNAI1 as markers for high-risk colorectal adenomas." (PMID 23029563, 2012). "Analysing an unselected cohort of colorectal adenomas, we were therefore surprised by the relatively high frequency of SNAI1 and TWIST1 mRNA expression, which was quite similar to the published expression rates in CRC tissue." (PMID 23029563, 2012). "SNAI1 mRNA was expressed in 78% (n = 32/41), TWIST1 mRNA in 41% (n = 17/41) and CDH2 mRNA in 41% (n = 17/41) of the colorectal adenoma tissue, while normal colon mucosa was negative for these transcription factors." (PMID 23029563, 2012).
colorectal tumor (2 papers, 2011 to 2024). "We hypothesize that the expression level of TWIST1 in primary colorectal tumors determines the characteristics of the tumors, their behavior and their clinical outcome." (PMID 21464926, 2011).
cutaneous melanoma (2 papers, 2022 to 2023). A primary melanoma arising from atypical melanocytes in the skin. "Survival analysis in cutaneous melanoma patients showed that high TWIST1 and ZEB1 expression was associated with a shorter metastasis-free survival." (PMID 35682684, 2022). "Normal cutaneous melanocytes have a high expression of SNAI2 and ZEB2 and a low expression of ZEB1 and TWIST1, while malignant cutaneous melanomas have low SNAI2 and ZEB2 and high ZEB1 and TWIST1." (PMID 35682684, 2022).
depression (2 papers, 2022 to 2025). "It is worth noting that not every instance of CID can be attributed to the EVs-packaged Twist1 pathway, given that cancer and depression converge on several key pathophysio-logical mechanisms, including inflammation and aberrant neurotransmission." (PMID 40963917, 2025). "Some studies showed that Twist family BHLH transcription factor 1 (TWIST1) in the prefrontal cortex was a key molecule that mediated depression-like behaviour in mice." (PMID 35562946, 2022). "TWIST1 knockout effectively improved depression-like behaviour such as anhedonia and failure of social interaction in CUMS mice." (PMID 35562946, 2022). "Finally, the present study did not examine Twist1 expression changes in SDEVs from clinical cancer patients with comorbid depression." (PMID 40963917, 2025).
dilated cardiomyopathy (2 papers, 2016 to 2024). Cardiomyopathy which is characterized by dilation and contractile dysfunction of the left and right ventricles. "In the treatment of dilated cardiomyopathy, TWIST1 acts as an advantageous target to improve heart quality by increasing miR-199/214 cluster expression and decreasing UPS activity." (PMID 38515760, 2024). "Notably, miR-199/214 cluster expression was positively regulated by the transcription factor TWIST1, which might be used as a preregulator for miR-199/214/UPS-involved dilated cardiomyopathy." (PMID 38515760, 2024).
esophageal tumor (2 papers, 2011 to 2022). "Among them, TWIST1 as well as two ZEBs were over-expressed in the two sets of esophageal tumors." (PMID 21533028, 2011).
fatty acid metabolic disorders (2 papers, 2022 to 2025). "Furthermore, Harmine, a Twist1 inhibitor, prevented fatty acid metabolic disorders and fibrogenesis, suggesting Twist1 could be a potential therapy target for AKI in the future." (PMID 40546823, 2025).
Fibroadenoma (2 papers, 2016 to 2025). A benign tumor of the breast characterized by the presence of stromal and epithelial elements. "TWIST1 exhibited significantly higher expression in fibroadenomas within the group exposed to the cafeteria diet." (PMID 40806434, 2025). "KRT5, TGF-β, PAI-1, HIF-1α, TIMP1, MMP2, TWIST1, VEGFα, and BRCA2 were all significantly upregulated in fibroadenomas." (PMID 40806434, 2025). "At 25 weeks, corresponding to fibroadenoma emergence, the Diet group showed increased expression of MMP2 (p = 0.036), THBS1 (p = 0.03), TWIST1 (p = 0.015), and PAI-1 (p < 0.001)." (PMID 40806434, 2025).
gallbladder cancer (2 papers, 2021 to 2024). "Moreover, overexpression of H19 in gallbladder cancer cells was shown to promote EMT and enhance cancer invasiveness by up-regulating the Twist-related protein 1 (Twist1)." (PMID 33402118, 2021).
heart failure (2 papers, 2011 to 2025). Inability of the heart to pump blood at an adequate rate to meet tissue metabolic requirements. "Here, we generated transgenic mice with over-expression of Hand1 and Twist1 mutants (to mimic or to abolish phosphorylation) in cardiomyocytes and found pathological cardiac remodeling leading to heart failure and sudden death." (PMID 21559426, 2011).
intimal sarcoma (2 papers, 2023 to 2025). A malignant neoplasm arising from the large blood vessels. "Nevertheless, the finding that TWIST1 was associated with favorable drug response in intimal sarcoma is cause for further work in this area." (PMID 38139368, 2023). "Furthermore, in a recent clinical trial of an MDM2 inhibitor, milademetan, for intimal sarcoma in Japan, TWIST1 expression was associated with favorable responses." (PMID 38139368, 2023). "Recent evidence from studies of milademetan in intimal sarcoma suggests that cyclin-dependent kinase inhibitor 2A (CDKN2A) loss and amplified twist-related protein 1 (TWIST1) may serve as additional biomarkers associated with enhanced anti-tumor activity in MDM2-amplified tumors." (PMID 41170373, 2025).
intrahepatic cholangiocarcinoma (2 papers, 2019 to 2021). A carcinoma that arises from the intrahepatic bile duct epithelium in any site of the intrahepatic biliary tree. "MiR-214 was also deemed as an intrinsic modulator of EMT by targeting Twist1 in intrahepatic cholangiocarcinoma." (PMID 30646925, 2019). "The dysregulation of human Twist1 has been reported in HCC and other cancers, and research suggests that Twist1 plays an important role in promoting the invasion and metastasis of HCC and intrahepatic cholangiocarcinoma." (PMID 34577566, 2021).
kidney (2 papers, 2020 to 2021). "During prostate carcinogenesis, EMT is related to cancer progression, migration and metastasis, and mesenchymal markers and transcription factors, such as vimentin, N-cadherin, Snai1, and Twist1/2, are highly upregulated." (PMID 34298624, 2021).
malignant peripheral nerve sheath tumor (2 papers, 2014 to 2019). Malignant peripheral nerve sheath tumor (MPNST) is a rare and often aggressive soft tissue sarcoma occurring in a wide range of anatomical sites. "EMT-associated transcription factors such as SNAIL (SNAI1), SLUG (SNAI2), Twist Family BHLH Transcription Factor (TWIST)-1, Zinc Finger E-Box Binding Homeobox (ZEB) have been shown to be upregulated in malignant peripheral nerve sheath tumor (MPNST) deficient for neurofibromin." (PMID 30967630, 2019). "While Twist1 is largely absent from adult differentiated tissues, it is expressed in diseased heart valves and highly metastatic cancers such as breast, pancreatic, gastric, prostate, and malignant peripheral nerve sheath tumors (MPNST)." (PMID 25262113, 2014).